MAGED2 (MAGE family member D2)
Description:
Regulates the expression, localization to the plasma membrane and function of the sodium chloride cotransporters SLC12A1 and SLC12A3, two key components of salt reabsorption in the distal renal tubule.
Synonyms: BCG-1; BCG1; JCL-1; 11B6; MAGE-D2; HCA10; MAGED; MGC8386; BARTS5
Tractability: Antibody: its Gene Ontology location is reachable by antibodies, with high confidence. PROTAC: ubiquitination databases record sites on it; its protein half-life has been measured.
Gene: Protein-coding gene on chromosome X (54,807,599 to 54,816,015, forward strand). Ensembl gene ENSG00000102316.
Subcellular location (Human Protein Atlas): Cytosol; Nucleoli; Nucleoplasm
Pathways (Reactome):
Hemostasis: Platelet degranulation
Gene Ontology:
Molecular function: protein binding
Biological process: female pregnancy; renal sodium ion absorption; negative regulation of transcription by RNA polymerase II
Cellular component: cytosol; membrane; nucleolus; nucleoplasm; extracellular region; nucleus; platelet alpha granule lumen
Gene-disease validity (ClinGen):
ClinGen rates the evidence that MAGED2 causes each of these diseases.
Bartter disease type 5 (X-linked): Definitive.
Homologues: Orthologues: chimpanzee MAGED2 (99% identical), macaque MAGED2 (99% identical), dog MAGED2 (88% identical), rat Maged2 (87% identical), mouse Maged2 (87% identical), rabbit MAGED2 (85% identical), zebrafish ndnl2 (17% identical), Drosophila melanogaster MAGE (9% identical). Paralogues in human: TRO (49% identical), MAGED1 (43% identical), MAGED4 (36% identical), MAGED4B (36% identical), MAGEL2 (26% identical), MAGEE1 (23% identical), MAGEF1 (22% identical), MAGEB17 (20% identical), MAGEB18 (20% identical), MAGEB10 (19% identical), NDN (19% identical), MAGEB16 (19% identical), and 25 more.
Diseases named in the same sentence as MAGED2 in open-access papers:
MAGED2 is named in the same sentence as 45 diseases in open-access papers, as found by Europe PMC text mining. Sharing a sentence is not in itself a finding about the gene and the disease. The quoted sentences say what the papers report.
Bartter syndrome (26 papers, 2018 to 2026). "Whole-exome sequencing (WES) excluded pathogenic variants in renal tubulopathy genes including SLC12A3 (Gitelman syndrome), SLC12A1, CLCNKB, BSND, KCNJ1, MAGED2 (Bartter syndrome), and CASR, CLCNKA, KCNJ10 (hypokalemia-associated genes)." (PMID 40893942, 2025). "Hemizygous variants in ABCB7, ALAS2, and MAGED2, associated with X-linked recessive disorders (sideroblastic anemia and antenatal Bartter syndrome), can manifest with hydrops or anemia in utero in affected males." (PMID 41256177, 2025). "Mutations in MAGED2 cause transient antenatal Bartter syndrome (tBS) characterized by excessive amounts of amniotic fluid due to impaired renal salt transport via NKCC2 and NCC, high perinatal mortality, and pre-term birth." (PMID 39936967, 2025). "Recently, an X-linked antenatal form of Bartter syndrome has been identified that causes a transient syndrome due to a mutation in the melanoma-associated antigen D2 (MAGED2) gene." (PMID 39405114, 2024). "The antenatal form, specifically type 5, of Bartter syndrome caused by MAGED2 gene mutation is a life-threatening condition." (PMID 38238844, 2024). "Among these genes, MAGED2 mutations are associated with the transient form of Bartter syndrome, which is usually called Antenatal Bartter syndrome caused by mutations in the MAGED2 gene located on chromosome Xp11." (PMID 38238844, 2024). "Disruptions in the expression or activity of NKCC2 and NCC due to MAGED2 mutations can lead to the characteristic symptoms observed in Antenatal Bartter syndrome." (PMID 38238844, 2024). "Antenatal Bartter syndrome is a life-threatening disease caused by a mutation in the MAGED2 gene located on chromosome Xp11." (PMID 38238844, 2024). "Mutations in MAGED2 cause transient Bartter syndrome characterized by perinatal loss of urinary concentration capability and large urine volumes." (PMID 37439567, 2023). "Mutations in MAGED2 cause transient Bartter syndrome characterized by severe renal salt wasting in fetuses and infants, which leads to massive polyhydramnios causing preterm labor, extreme prematurity and perinatal death." (PMID 36010623, 2022). "Mutations in the MAGED2 gene can cause X-linked acute early-onset polyhydramnios with a severe but transient form of antenatal Bartter's syndrome." (PMID 34926352, 2021). "We reported the first Chinese case of transient antenatal Bartter’s syndrome caused by MAGED2 mutation." (PMID 34895150, 2021). "We searched PubMed and Google Scholar using the following terms: “MAGED2 AND mutation AND (Polyhydramnios or Bartter's Syndrome)” to search all the literature to summarize all cases of polyhydramnios or Bartter's syndrome caused by an MAGED2 mutation." (PMID 34926352, 2021). "Transient antenatal Bartter’s syndrome caused by MAGED2 mutation is a rare X-linked recessive renal tubular disorder." (PMID 34895150, 2021). "We identified a novel variant (c.1598C > T, p.Ala533Val) in MAGED2 by next generation sequencing in a Chinese preterm neonate with transient antenatal Bartter’s syndrome phenotype." (PMID 34895150, 2021). "Variants in the MAGED2 may cause antenatal transient Bartter syndrome, which is characterised by polyhydramnios, preterm labour, postnatal polyuria, hypokalaemia and metabolic alkalosis." (PMID 36819197, 2023). "Moreover, we previously showed that MAGED2 mutations cause transient Bartter syndrome characterized by severe renal salt wasting and polyuria in fetuses, by heavily altering the expression of two critical renal salt-transporters, NKCC2, and NCC." (PMID 36359819, 2022). "Finally, a transient X-linked form of Bartter syndrome (type V Bartter syndrome) has been described in male patients harbouring mutations in the MAGED2 gene, which alters the expression of the NKCC2 and NCC, the sodium chloride cotransporter." (PMID 35137195, 2022).
Bartter syndrome (continued). "We recently demonstrated that MAGED2 is required for cAMP generation under hypoxia and proposed that this regulation may explain the transient nature of antenatal Bartter syndrome (aBS) due to MAGED2 mutations." (PMID 36359819, 2022). "This may explain, at least in part, the transient nature of Bartter syndrome caused by MAGED2 mutations and opens new avenues for therapy in these patients." (PMID 36010623, 2022). "MAGED2 mutations can cause a form of transient antenatal Bartter’s syndrome." (PMID 33752626, 2021). "However, a rare, severe, but transient form of antenatal Bartter's syndrome due to an x-linked melanoma-associated antigen D2 (MAGED2) mutation has recently been described." (PMID 29594084, 2018). "In this report, we present a case of antenatal Bartter syndrome with a novel pathogenic deletion in the intron of the MAGED2 gene and we report here, for the first time, a female fetus carrying a pathogenic heterozygous variant in the MAGED2 gene, which can also result in antenatal Bartter syndrome." (PMID 38238844, 2024). "Hence, the spontaneous resolution of transient Bartter’s syndrome caused by MAGED2 mutations may result from a developmental increase in oxygen supply to the kidney, which renders MAGED2 dispensable as Gαs can function independently under normoxia." (PMID 37686237, 2023). "Accordingly, recent evidence has indicated that MAGE proteins may play a role in renal pathophysiology: It has been reported that MAGED2 is essential for fetal renal salt reabsorption and that MAGED2 mutations cause transient form of antenatal Bartter’s syndrome." (PMID 34788311, 2021). "Background/Objectives: We aimed to report three novel MAGED2 variants associated with transient antenatal Bartter syndrome and to summarize the prenatal and postnatal features of MAGED2-related TABS through case analysis and literature review." (PMID 42074542, 2026). "Recent reports suggested that melanoma-associated antigen D2 (MAGED2) is a novel regulator of NKCC2, a gene identified by whole-exome sequencing in families affected by transient antennal Bartter’s syndrome with polyhydramnios." (PMID 39717823, 2024). "Bartter syndrome is classified into five major genotypes caused by mutations in different genes, namely SLC12A1, KCNJ1, CLCNKB, CLCNKA, BSND, and MAGED2." (PMID 38238844, 2024). "CtermMAGEL2p.R1187C was modeled on a pathogenic missense mutation in a highly conserved arginine residue in the second of two tandem winged helix motifs (WH-B) in the MHD of MAGED2 identified in a patient with Bartter syndrome." (PMID 34265304, 2021). "Melanoma-associated antigen D2 (MAGED2) plays an essential role in activating the cAMP/PKA pathway under hypoxic conditions, which is crucial for stimulating renal salt reabsorption and thus explaining the transient variant of Bartter’s syndrome." (PMID 37686237, 2023). "In transient Bartter syndrome, dysregulation of NCC is evidenced by its aberrant expression in the fetal kidney in a tBS patient, a finding corroborated in vitro by showing significantly increased NCC cell surface expression upon MAGED2 overexpression." (PMID 39936967, 2025). "Thus, we demonstrated that MAGED2 is required for the activation of the cAMP/PKA pathway under hypoxic conditions to regulate Gαs endocytosis via MDM2-dependent ubiquitination, thereby explaining, at least in part, the transient nature of transient Bartter syndrome." (PMID 36010623, 2022).
breast cancer (7 papers, 2014 to 2025). A primary or metastatic malignant neoplasm involving the breast. "MAGED2 mutations are also involved in several cancers, including breast cancer and melanoma." (PMID 33752626, 2021). "MAGED2 exhibits distinct effects depending on the subtype of breast cancer." (PMID 37996875, 2023).
melanoma (6 papers, 2015 to 2024). A malignant, usually aggressive tumor composed of atypical, neoplastic melanocytes. "Among others, we also found proteins such as MAGED2, a melanoma-associated antigen that has also been involved in cell cycle progression, modulation of DNA damage response, and melanoma metastasis." (PMID 39272836, 2024). "In addition, MAGED2 is able to suppress the expression of TRAIL death receptor 2 (TRAIL-R2) and plays an important role in protecting melanoma cells from apoptosis induced by TRAIL, thus it has been recognized as a cancer diagnostic marker." (PMID 37439567, 2023).
gastric cancer (5 papers, 2018 to 2025). A primary or metastatic malignant neoplasm involving the stomach. "Further studies have confirmed that MAGED2 expression levels were associated with the metastatic potential of gastric cancer, indicating that patients with gastric cancer had a poor prognosis." (PMID 35892426, 2022). "We reported that increased levels of tissue and serum MAGED2 were associated with distant metastasis in gastric cancer." (PMID 29721160, 2018). "The distinct roles of SYT8 and MAGED2 in the progression of gastric cancer synergistically enhanced predictive performance, achieving stratification that is more precise." (PMID 29733517, 2018). "This research explores the prognostic signature of MAGED2, KEAP1, GLA, EIF1AD, and EHF genes associated with hypoxia in gastric cancer through analyzing transcriptome information and scRNA-seq data, and indicates the clinical relevance of hypoxia during gastric cancer progression." (PMID 40129974, 2025). "Furthermore, numerous studies have shown that MAGED2 is a tumor-specific antigen that plays an important role in tumor progression and metastasis, including hepatocellular carcinoma, gastric cancer, and lymphoma." (PMID 35892426, 2022). "The four constituents of the expression panel, MAGED2, SYT8, BTG1, and FAM46, have individual roles in gastric cancer progression." (PMID 29721160, 2018).
acute kidney injury (3 papers, 2021 to 2023). Sudden and sustained deterioration of the kidney function characterized by decreased glomerular filtration rate, increased serum creatinine or oliguria. "Previously, induction of MAGED2 in the distal tubule in folic-acid induced acute kidney injury has been reported, in keeping with a role of MAGED2 in the protection against stress by preserving renal salt reabsorption in AKI." (PMID 37686237, 2023). "Other investigators have reported that five MAGE genes (MAGED1, MAGED2, MAGED3, MAGEH1, MAGEE1) are expressed in healthy adult mouse kidneys and that MAGED2 is upregulated during an experimental acute kidney injury." (PMID 34788311, 2021). "The biological implications of MAGED2’s role in amplifying hypoxic induction of HIF-1α are broad because MAGED2 is expressed in many adult tissues where it could play a critical role under hypoxic conditions (i.e., high altitude, inflamed hypoxic tissue, acute kidney injury, and cancer)." (PMID 36359819, 2022).
glioma (3 papers, 2020 to 2024). A benign or malignant brain and spinal cord tumor that arises from glial cells (astrocytes, oligodendrocytes, ependymal cells). "The goal of current research aims to investigate the MAGED2 gene’s potential as a cancer-associated tumor marker, which might serve as a beneficial prognostic biomarker and immunotherapeutic target for glioma." (PMID 35892426, 2022). "Firstly, the goal of this study was to determine the changes in MAGED2 expression between glioma and normal brain tissue, as well as the impact of MAGED2 on the prognosis of glioma patients." (PMID 35892426, 2022). "CCK-8 and colony formation experiments were performed on glioma U251-MG cells transfected with MAGED2 CRISPR or Scramble CRISPR to better understand the role of MAGED2 in glioma cell proliferation." (PMID 35892426, 2022). "MAGED2 expression in 98 glioma tissues was measured using RT-qPCR, Western blot, and immunohistochemistry." (PMID 35892426, 2022). "MAGED2 is often overexpressed in human glioma tissues, which predicts a poor prognosis for glioma patients." (PMID 35892426, 2022). "Thirdly, a MAGED2 CRISPR KO-expressing lipofectamine vector was created and transfected into glioma U251-MG cells, allowing it to stably downregulate MAGED2’s expression levels in vitro." (PMID 35892426, 2022). "The percentage of cells in low-grade glioma samples that expressed MAGED2-positive protein was 30.61%, whereas it was 48.97% in high-grade gliomas." (PMID 35892426, 2022). "There was a significant association between glioma grading and IDH1/2 (p < 0.05), 1p/19q (p < 0.05), MGMT (p < 0.05), Ki67 (p < 0.01), and MAGED2 (p < 0.01)." (PMID 35892426, 2022). "The expression levels of MAGED2 were analyzed in 98 glioma and 16 normal brain tissue specimens using RT-qPCR and Western blotting." (PMID 35892426, 2022). "In conclusion, the current study found that MAGED2 plays an important role in the prognosis and growth of human glioma." (PMID 35892426, 2022). "There were significant differences between low- or high-grade glioma compared with normal brain tissues for MAGED2 mRNA levels (p < 0.001)." (PMID 35892426, 2022). "In patients with glioma, a substantial positive correlation between MAGED2 protein expression, OS, and RFS times were discovered using clinical records." (PMID 35892426, 2022). "According to the HPA database, the overall proportion of positive cells for MAGED2 protein in glioma was 100%." (PMID 35892426, 2022). "Overall, these data demonstrated that MAGED2 plays a key role in glioma growth and expansion in vivo." (PMID 35892426, 2022). "As a result of these three tests, it was concluded that knocking-down MAGED2 inhibited the proliferation of glioma U251-MG cells." (PMID 35892426, 2022). "As a result, the MAGED2/CDKN1A pathway may be related to the G1 phase of the cell cycle in glioma U251-MG cells." (PMID 35892426, 2022). "We also discovered that MAGED2 regulates glioma U251-MG cell growth via CDKN1A." (PMID 35892426, 2022). "As a result, the data suggest that MAGED2 may increase the proliferation of glioma U251-MG cells by inhibiting CDKN1A." (PMID 35892426, 2022). "Furthermore, as compared to NBTs, MAGED2 was shown to be substantially expressed in human glioma tissues." (PMID 35892426, 2022). "Since there was a substantial positive relationship between high MAGED2 protein expression and glioma prognosis, it was assumed that MAGED2 protein expression may be identified as an independent prognostic factor for glioma patients." (PMID 35892426, 2022). "Finally, our findings showed that downregulating MAGED2 in vivo will decrease glioma tumor growth by increasing CDKN1A expression." (PMID 35892426, 2022). "IHC was used to examine MAGED2 protein expression in 98 glioma tissues." (PMID 35892426, 2022). "In the CGGA database, the expression of MAGED2 rose dramatically as the grade of glioma increased." (PMID 35892426, 2022).
glioma (continued). "Moreover, the CGGA database results revealed that the expression of MAGED2 increased dramatically as the grade of glioma increased." (PMID 35892426, 2022). "MAGED2 could be used as an independent predictive biomarker in glioma patients, according to multivariate and univariate survival studies." (PMID 35892426, 2022). "Furthermore, the downregulation of MAGED2 expression by MAGED2 CRISPR inhibited the proliferation of glioma U251-MG cells in vitro by upregulating CDKN1A." (PMID 35892426, 2022). "As a result, the precise involvement of MAGED2 in the progression and prognosis of glioma patients remains unknown." (PMID 35892426, 2022). "The downregulation of MAGED2 expression inhibited the growth of glioma cells in our investigation." (PMID 35892426, 2022). "Furthermore, the impact of MAGED2 knockdown on apoptosis in glioma U251-MG cells was also investigated." (PMID 35892426, 2022). "In vitro, knocking-down MAGED2 would stop glioma cells from proliferating." (PMID 35892426, 2022). "However, whether other key elements are also involved in MAGED2’s regulatory network in glioma warrants additional investigation." (PMID 35892426, 2022). "However, the expression intensity of MAGED2 protein is differential in gliomas." (PMID 35892426, 2022). "Furthermore, by examining the Oncomine microarray datasets, researchers may detect variations in MAGED2 mRNA expression in distinct types of gliomas." (PMID 35892426, 2022). "Furthermore, these findings suggest that MAGED2 can stimulate the growth of U251-MG cells by targeting CDKN1A, suggesting that MAGED2 may serve as a novel target in the clinical treatment of glioma." (PMID 35892426, 2022). "However, the mechanism and function of MAGED2 in glioma remain unknown." (PMID 35892426, 2022). "The WHO classification, IDH1 status (Mutant), and MAGED2 protein expression were all found to have a substantial influence on OS and RFS in patients with glioma." (PMID 35892426, 2022). "However, the precise function and mechanism of MAGED2 in glioma is still unknown." (PMID 35892426, 2022). "The GFP-expressing MAGED2 CRISPR and Scramble CRISPR were created and transfected into U251-MG cells to better understand the role of MAGED2 in glioma." (PMID 35892426, 2022). "The positive control was a known glioma tissue segment with MAGED2-positive expression, while the negative control was the omission of the primary antibody." (PMID 35892426, 2022). "Future in vitro and in vivo investigations should use MAGED2-positive and -negative glioma cells to determine the biological function of MAGED2." (PMID 35892426, 2022). "Despite the long history of molecular research into the glioma profile, MAGED2 has never been published to our knowledge, even though we have established that it is an intriguing prognostic marker." (PMID 35892426, 2022). "MAGED2 protein was found in 24 cases of glioma but not in normal tissue." (PMID 35892426, 2022).
hepatocellular carcinoma (3 papers, 2015 to 2024). A malignant tumor that arises from hepatocytes. "MAGED2 mRNA overexpression leads to tumor growth in hepatocellular carcinoma, according to Kanda and colleagues, and thus may serve as a prognosis indicator after curative resection as well as a possible therapeutic target in hepatocellular carcinoma." (PMID 35892426, 2022).